PMS2 (PMS1 homolog 2, mismatch repair system component)
Diseases named in the same sentence as PMS2 in open-access papers (continued):
Sharing a sentence is not in itself a finding about the gene and the disease.
Lynch syndrome (continued). "Lynch syndrome is a hereditary disease characterized by constitutive mutations in the DNA mismatch repair pathway (most commonly MLH1, MLH2, MSH6, or PMS2 genes)." (PMID 37370964, 2023). "Only one (7%) SB-PCC (patient 12) exhibited an MMRd profile (loss of MLH1 and PMS2) and a PCC-NOS histology; this neoplasm arose in a 56-year-old male patient affected by Crohn disease; germline testing in such patient excluded Lynch syndrome." (PMID 36812376, 2023).
Lynch syndrome (continued). "This is known to be relatively common in Lynch syndrome cases with MLH1 variants, and only PMS2 expression is lost in most of these cases." (PMID 34185173, 2021). "Four patients (36%) had a germline mutation; two had paraganglioma syndrome type 4 (SDHB), one had a paraganglioma syndrome type 1 (SDHD), and one had Lynch syndrome (PMS2)." (PMID 32824391, 2020).
Lynch syndrome (continued). "Family history can also be misleading as pathogenic variants in PMS2, the gene implicated in more than 50% of CMMRD cases, have a much lower penetrance than other MMR variants in Lynch syndrome." (PMID 30740824, 2019). "Our results (2/51 = 4% with a hereditary cancer syndrome: Cowden and PMS2‐Lynch syndrome) are comparable to others." (PMID 30809968, 2019). "Remaining one case was confirmed for loss of MSH6 expression (HC137T), whereas the other for loss of PMS2 (HC8T), both of which were suspected of Lynch syndrome." (PMID 30680068, 2018). "When losses of both MLH1 and PMS2 proteins are observed by IHC, MLH1 promoter methylation analysis is conducted to distinguish Lynch syndrome-associated endometrial cancer from sporadic cancer." (PMID 29783979, 2018). "Of 204 patients with MLH1‐ and MLH1/PMS2‐deficient tumours, 199 (97·5 per cent) underwent reflex BRAF mutational testing to screen for Lynch syndrome, of whom 58 (29·1 per cent) were BRAF wild‐type." (PMID 30511046, 2018).
Lynch syndrome (continued). "Lynch Syndrome is a familial autosomal dominant condition characterized by a germline mutation in one of the MMR genes (90% - MLH1 and MLH2, 5-10% MSH6, PMS2)." (PMID 24653752, 2014). "Approximately 10 percent of Lynch syndrome families have a mutation in MSH6 and fewer families have a mutation in PMS2." (PMID 20487569, 2010). "Together with improvements in technology the ability to rapidly screen additional genes associated with Lynch syndrome, MSH6 and PMS2, has become available." (PMID 20487569, 2010).